CTNNB1 (catenin beta 1)
Diseases named in the same sentence as CTNNB1 in open-access papers (continued):
Sharing a sentence is not in itself a finding about the gene and the disease.
osteosarcoma (15 papers, 2013 to 2025). A usually aggressive malignant bone-forming mesenchymal neoplasm, predominantly affecting adolescents and young adults. "CTNNB1 is a transcriptional gene of the classical oncogenic protein β-catenin, and mutation in this gene abnormally activates the Wnt pathway in osteosarcoma, thus promoting tumour progression." (PMID 36844873, 2023). "Functional experiments demonstrated that circ-CTNNB1 overexpression markedly promotes osteosarcoma cell proliferation, invasion, and metastasis." (PMID 41403702, 2025). "For instance, Circ‐CTNNB1 promotes m6A modification by interacting with RBM15 in osteosarcoma cells to drive glucose metabolism reprogramming." (PMID 39661501, 2024). "Circ‐CTNNB1 was highly expressed in osteosarcoma (OS) tissues and predominantly detected in the nucleus of OS cells." (PMID 36181462, 2023). "LeXis has been reported to promote the growth of osteosarcoma through the upregulation of CTNNB1 expression." (PMID 33022942, 2020). "circ-CTNNB1 is highly expressed in osteosarcoma tissues and predominantly localized in the nucleus." (PMID 41403702, 2025). "Additionally, prior research has demonstrated that the interaction between RBM15 and circ‐CTNNB1 in osteosarcoma stimulates the growth of the tumour by promoting the expression of HK2." (PMID 39661501, 2024). "However, little is known about the role of circ‐CTNNB1 in osteosarcoma (OS), a highly malignant bone tumour in children and adolescents." (PMID 36181462, 2023). "This study highlights the critical role of the circ-CTNNB1/RBM15/m6A axis in metabolic reprogramming and osteosarcoma progression, offering a potential therapeutic target." (PMID 41403702, 2025). "For example, DANCR is able to upregulate CTNNB1 in HCC, and activate AKT pathway in osteosarcoma." (PMID 31804607, 2020). "Since our present findings associate cytoplasmic p27 localization with the metastatic potential of osteosarcoma cells, we evaluated the mRNA levels of the set of metastatic markers, VIM, SNA2, CDH2, CTNNB1 and STMN1 following XPO1 inhibition and AZD1775 exposure, by RT-qPCR." (PMID 30992462, 2019). "In addition, RBM15 interacts with circ-CTNNB1 to enhance the expression of HK2, GPI and PGK1 in an m6A modification-dependent manner, leading to the promotion of the glycolytic process and the development of osteosarcoma." (PMID 37474926, 2023).
colorectal tumors (14 papers, 2005 to 2022). "β-catenin (CTNNB1) is the most frequently mutated gene, and it can be detected in more than 80% of colorectal tumors." (PMID 33723286, 2021). "Moreover, human and feline colorectal tumors harbor the same mutations of the CTNNB1 gene, encoding β-catenin." (PMID 34885050, 2021). "From a comparative point of view, in intestinal neoplasms in dogs, CTNNB1 mutations were proven to be more often causative than APC mutations, with CTNNB1 being mutated in >60% of canine colorectal tumors." (PMID 34885050, 2021). "Wnt signaling is ubiquitously activated in colorectal tumors and driver mutations are identified in genes such as APC, CTNNB1, RNF43 and R-spondin (RSPO2/3)." (PMID 33202731, 2020). "We showed that ELF3 exhibits mutually exclusive patterns of expression with CTNNB1/ β-catenin across colorectal tumour panels and that ELF3 is an antagonist of Wnt/β-catenin and RAS signalling-induced EMT." (PMID 30148686, 2019). "Approximately 90% of sporadic colorectal tumors carry a mutation in APC and up to 5% in the CTNNB1 gene." (PMID 31614493, 2019). "Taken together, these data suggest that the heightened inflammatory and proliferative state observed in the context of the Il10−/− mouse colon coupled with AOM-induced activation of the WNT/CTNNB1 pathway results in an increased propensity for colorectal tumor formation and progression." (PMID 19551144, 2009). "The early to intermediate stages of the majority of colorectal tumours are thought to be driven by aberrations in the Wnt (APC, CTNNB1) and Ras (K-ras) pathways." (PMID 16356174, 2005). "Both β-catenin (CTNNB1) and adenomatous polyposis coli (APC), which is a negative regulator of β-catenin stability, are frequently mutated genes in colorectal tumors." (PMID 26107817, 2015).
endometriosis (14 papers, 2018 to 2025). The growth of functional endometrial tissue in anatomic sites outside the uterine body. "CTNNB1 mutation was detected in many cancers including ovarian or endometrial type as well as in endometriosis." (PMID 35012617, 2022). "Moreover, different types of gene-based biomarkers such as ARID1A, PIK3CA, KRAS and CTNNB1 are recurrently mutated in endometrial cancer type I, endometriosis and endometriosis-associated ovarian tumors." (PMID 37189525, 2023). "In summary, LINC02381 may be able to upregulate CTNNB1 by adsorbing miR-27b-3p, causing increased migration and invasion of ESCs, thus leading to the occurrence and development of endometriosis." (PMID 35327987, 2022). "Since both papers demonstrate an upregulation of CTNNB1 in endometrial stromal cells in endometriosis lesions, we can raise the question of an additional important role for CTNNB1 action in the epithelium of endometriosis lesions." (PMID 37005590, 2023). "Increased expression of CTNNB1 was seen in presented endometriosis patients of EG when compare to CG." (PMID 35012617, 2022). "In particular, researchers believe that CTNNB1 can support endometriosis progression by promoting the proliferation and invasion of ESCs." (PMID 35327987, 2022). "Determination of genes expression CTNNB1 and HIF1A helps to allocate risk patients with endometriosis where more precise management is needed." (PMID 35012617, 2022). "The aim of this study was to investigate the mechanism of interaction between LINC02381 and CTNNB1 in endometriosis." (PMID 35327987, 2022). "Taking into account both subgroups we can conclude that CTNNB1 expression correlates with the endometriosis extent in patients." (PMID 35012617, 2022). "In addition, the LINC02381/miR-27b-3p/CTNNB1 axis could promote the proliferation and invasion of ESCs, thereby accelerating the development of endometriosis." (PMID 35327987, 2022). "Thus, CTNNB1 is a key factor in the regulation of proliferation and invasion in endometriosis." (PMID 35327987, 2022). "Thus, CTNNB1 may be involved in the pathogenesis of endometriosis by participating in the mesenchymal-to-epithelial transition and epithelial-to-mesenchymal transition processes." (PMID 35327987, 2022). "Conventional cytogenetics as well as measurement of transcriptional activity of CTNNB1 (β-catenin) and HIF1A (HIF1-α) genes were prospectively studied in 60 endometriosis patients and 50 control group patients." (PMID 35012617, 2022). "Moreover, researchers have suggested that CTNNB1 regulation could lead to distortion in the mesoderm, which in turn would promote the abnormal localization of stem cells and induce the occurrence of endometriosis." (PMID 35327987, 2022). "This group - transcriptionally evident endometriosis (TEE), contained 34 patients from EG where the level of mRNA genes (HIF1A and CTNNB1) were significantly higher compared to the both, CG as well as TIE." (PMID 35012617, 2022). "Nevertheless, the LINC02381/miR-27b-3p/CTNNB1 regulatory axis identified in this study may offer insights into the diversity and complexity of lncRNA/mRNA interactions and contribute to the application of such biomarkers in the future diagnosis of endometriosis." (PMID 35327987, 2022).
endometriosis (continued). "To further verify that the LINC02381/miR-27b-3p/CTNNB1 regulatory axis is involved in proliferation and invasion in endometriosis and to clarify the role of LINC02381 in endometriosis, we designed the following experiments." (PMID 35327987, 2022). "This study was performed to investigate the regulatory effect of LINC02381 on CTNNB1 and on ESC proliferation and invasion in endometriosis." (PMID 35327987, 2022). "Transcriptionally incipient endometriosis (TIE), with 26 patients showed increased level of gene mRNA for both, HIF1A and CTNNB1 compared to CG however significantly lower than in second group." (PMID 35012617, 2022). "Importantly, it has been reported that, with regard to perimenopausal endometriosis, endometrioid ovarian carcinomas (ENOC) and clear cell ovarian carcinomas (CCOC) are associated with mutations of ARID1A, a tumor suppressor gene, PTEN, KRAS and -catenin (CTNNB1) genes." (PMID 30870972, 2019). "Catenin Beta 1 (CTNNB1), on the other hand, which is likewise upregulated in DIE epithelial cells compared to cells from adenomyosis, is discussed as a key factor in the regulation of proliferation and invasion of endometriosis." (PMID 37005590, 2023). "In light of the ceRNA network provided by our whole-transcriptome sequencing analysis, it was possible to screen potential downstream targets of LINC02381, among which the LINC02381/miR-27b-3p/CTNNB1 regulatory axis was identified in OSA and ESCs of patients with endometriosis." (PMID 35327987, 2022). "The relationship between level of HIF-1α and CTNNB1 and the potential of endometriosis malignization was not studied yet." (PMID 35012617, 2022). "In general, both endometrioid and clear cell ovarian cancer with or without endometriosis have common high frequency mutations in ARID1A, PIK3CA, catenin betat 1 (CTNNB1), PTEN, and KRAS." (PMID 30087267, 2018). "On the other hand, simultaneous inhibition of miR-27b-3p and LINC02381 induced the expression of CTNNB1, which in turn, enhanced the proliferation of ESCs, suggesting that the LINC02381/miR-27b-3p/CTNNB1 axis is a potential prognostic biomarker and therapeutic target for endometriosis." (PMID 35327987, 2022).
glioblastoma (13 papers, 2020 to 2025). The most malignant astrocytic tumor (WHO grade IV). "CTNNB1 mutations are rare in glioblastoma, unlike other cancers." (PMID 40564017, 2025). "Furthermore, TRIM33 acts as a tumor suppressor by degrading CTNNB1 in human glioblastoma." (PMID 39062881, 2024). "Through this study, it is evident that targeting the CTNNB1/TCF and autophagy pathways behaves as a potential therapeutic option, indicating the importance of β-catenin and, ultimately, CTNNB1 in glioblastoma cell viability." (PMID 40564017, 2025). "Another study using anti-diabetic drug pioglitazone in Glioblastoma Multiforme lowered beta-catenin level, creating potential ground for T2DM therapeutic intervention studies targeting CTNNB1." (PMID 39281650, 2024). "To further investigate the effect of FMRP on these mRNAs in glioblastoma, we detected WNT5B and CTNNB1 mRNA levels in an aggressive commercial glioblastoma cell line, namely T98G." (PMID 35982038, 2022).
schizophrenia (13 papers, 2016 to 2024). A major psychotic disorder characterized by abnormalities in the perception or expression of reality. "Another synaptic hub protein that is implicated in AD and schizophrenia, β-catenin (CTNNB1), is a core participant in Wnt-signaling, and the number of ribosome-associated CTNNB1 transcripts is down-regulated in the Apoer2cKO." (PMID 37461529, 2023). "Another synaptic hub protein that is implicated in AD and schizophrenia, β-catenin (CTNNB1), is a core participant in Wnt-signaling, and the number of translating CTNNB1 transcripts is down-regulated in the Apoer2cKO." (PMID 37726747, 2023). "CTNNB1 also contains damaging genetic variants in several neurodevelopmental disorders, including schizophrenia, while some antipsychotic drugs result in increased levels of β-catenin in the brain." (PMID 33193575, 2020). "Limited studies have reported CTNNB1 mutations in schizophrenia." (PMID 37009120, 2023). "DISC1 is now established as a risk factor for schizophrenia and other major psychiatric illness and is involved in aspects of adult progenitor proliferation, neurogenesis, neurite outgrowth, cytoskeletal modulation, signal transduction, and CTNNB1 abundance." (PMID 34831151, 2021). "β-catenin is encoded by CTNNB1, a gene related to cognitive disorders entailing language deficits, particularly to schizophrenia, but also to genes that have been hypothesized to contribute to language evolution in our species [see for details]." (PMID 29922639, 2018). "Moreover, mutations in the CTNNB1 gene (c.1943 A>G) are associated with schizophrenia, whilst CTNNB1 KO mice display anxiety behaviors and CTNNB1 KO in paraventricular interneurons accompanied by impairments in social interactions, repetitive behaviors, and object recognition." (PMID 34831151, 2021). "All these genes are associated with psychiatric conditions, ranging from ID i.e., CNKSR2, CTNNB1, ANK3, CASK and ASD i.e., CTNND2, ANK3 to schizophrenia i.e., CNKSR2 (GWAS, PGC-SCZ 2014) and bipolar disorder ANK3." (PMID 28713243, 2017). "Similarly, the mRNA expression of CTNNB1 and GSK3β remained unchanged in the DLPFC of patients with schizophrenia." (PMID 39061390, 2024). "Interestingly, CTNNB1, an essential component in the WNT signalling pathway and a 3′-flanking gene of ULK4, participates in hippocampal network regulation and contributes to the decreased GAD67 expression in both schizophrenia and bipolar patients." (PMID 27670918, 2016).
autism (12 papers, 2014 to 2025). Persistent deficits in social interaction and communication and interaction as well as a markedly restricted repertoire of activity and interest as well as repetitive patterns of behavior. "A recent cohort study identified CTNNB1 mutations affecting both adhesive and regulatory domains, with associated features ranging from motor dysfunction to autism spectrum traits." (PMID 40766181, 2025). "Different publications have indicated that mutations in the CTNNB1 gene are associated with both cancer and autism." (PMID 37807632, 2023). "CTNNB1 is identified as a category 1 gene (strong candidate ASD gene) according to the Simons Foundation Autism Research Initiative (SFARI) database." (PMID 37009120, 2023). "Third, through network toxicology, single-cell transcriptomics, and animal experimentation, we demonstrate that chronic PM2.5 exposure exacerbates valproic acid-induced autism-like behaviors in murine models, identifying CTNNB1, PTEN, CCR2, AKT1, and mTOR as potential core mediating genes." (PMID 41304474, 2025). "A systematic review was conducted to examine previous research that provided CTNNB1 syndrome patients, specifically those that described intellectual quotient, motor development, language impairments, behavioural problems and features of autism." (PMID 39976812, 2025). "Interestingly, according to the Simons Foundation Autism Research Initiative (SFARI) database, CTNNB1 nonsense and missense mutations have been reported in ASD subjects." (PMID 37908488, 2023). "CTNNB1 protein and CREB‐binding protein (CREBBP) exist in all autism networks, except for the APPIN2." (PMID 37807632, 2023). "Moreover, autistic disorder was among disease alliance enriched terms, and included MAPK1 and CTNNB1 proteins (FDR = 0.044)." (PMID 37908488, 2023).
leukemia (12 papers, 2011 to 2025). A malignant (clonal) hematologic disorder, involving hematopoietic stem cells and characterized by the presence of primitive or atypical myeloid or lymphoid cells in the bone marrow and the blood. "In AML-mesenchymal stromal cells (MSCs)-CD34+ cells co-cultured system, this a novel COX2/NR4A1/CTNNB1 axis increased leukaemia-reactive T-effector cells and rescued cellular metabolism and anti-leukaemia immunity." (PMID 36052242, 2022). "DBF activates the expression of genes encoding the proteins involved in leukemia cell survival, such as KIT, CTNNB1, CCNE1, NFKB1, E2F1, and downregulates the expression of CCND2, CCNA1, and FLT3 genes." (PMID 34564151, 2021). "Its interactions with CTNNB1 (β-catenin) and MAP kinase components indicate a regulatory function in the Wnt/β-catenin and MAPK signaling pathways, which are frequently dysregulated in leukemia." (PMID 40564907, 2025). "Ash1l, Ctnnb1, Hoxa7, and Hoxa9 were also upregulated in the single mutant Mir-142−/− GMPs compared to WT, but the key co-factors Meis1 and Pbx3 were not, potentially explaining why these mice failed to develop leukemia." (PMID 33173219, 2020). "This leukemia variant depends on Wnt-β-catenin; the negative β-catenin regulator Apc is decreased and at the same time this leukemia is also characterized by high expression of ITGB3 as well as β-catenin (Ctnnb1) and High mobility group box 3 (Hmgb3)." (PMID 29342970, 2018).
Obesity (12 papers, 2016 to 2025). Accumulation of substantial excess body fat. "It has been proven in a study that whole-exome sequencing in young obese participants and revealed rare gain-of-function mutations in CTNNB1/β-catenin linked with increased obesity risk." (PMID 37600712, 2023). "Similarly, Ctnnb1/b-catenin was found to be linked with increased obesity risk in high-fructose and HFD models." (PMID 41007634, 2025). "To further assess the potential role of CTNNB1 in FTO-regulated chicken obesity development, we examined the expression of CTNNB1 in FTO-overexpressed and knockdown chicken preadipocytes." (PMID 36461116, 2022). "CTNNB1 (β-catenin) is a key regulator of fat expansion and human obesity." (PMID 33381155, 2020).
adrenocortical tumors (11 papers, 2013 to 2025). "Both AFF3 and ISM1 are known to be overexpressed in benign and malignant adrenocortical tumours with CTNNB1 mutation." (PMID 39167619, 2024). "Mutations in CTNNB1 gene over-activate the Wnt signaling pathway in human adrenocortical tumors." (PMID 35783357, 2022). "Therefore it can be speculated whether FGFR-signalling contributes to adrenocortical tumour growth by the upstream activation of WNT/beta catenin independently from activating mutations of CTNNB1." (PMID 32522271, 2020). "Of note, in the two samples with an abundance of AC1, we have observed a high expression of AFF3, ISM1 and LEF1, all known CTNNB1 target genes in both benign and malignant adrenocortical tumours." (PMID 39167619, 2024). "Like other adrenocortical tumors, activating mutations in CTNNB1 gene (encoding β-catenin) have also been documented in a subset of APA but the mechanism of CTNNB1 mutation activation of aldosterone production remains to be clearly defined." (PMID 34267727, 2021). "There are also results suggesting that adrenocortical tumors with molecular alterations of CTNNB1 are primarily nonsecreting adenomas (61.1%), but the role of the Wnt/β-catenin pathway in adrenocortical tumor size and cortisol production seems plausible." (PMID 32218328, 2020).